BRAF (B-Raf proto-oncogene, serine/threonine kinase)
Diseases named in the same sentence as BRAF in open-access papers (continued):
Sharing a sentence is not in itself a finding about the gene and the disease.
tumor (continued). "Molecular and morphologic tumor characteristics, such as KRAS/BRAF mutation status, mismatch repair (MMR) protein expression, tumor growth pattern, and tumor cell budding, have been shown to be of key therapeutic and/or prognostic relevance in CRC." (PMID 26106602, 2015). "Quantitative DNA methylation analysis demonstrated that approximately 20% of CRCs are CIMP tumours, and there are significant associations with old age, female sex, proximal colon location, poor differentiation, MSI and KRAS and BRAF mutations." (PMID 25622259, 2015). "Investigation of the anti-tumor immune response such as CD8 T-cell-rich infiltrate during combined BRAF and MEK-targeted therapy can also yield novel therapeutic strategies." (PMID 26143635, 2015). "In a recent study on 6155 randomized mCRC trial patients, tumor samples and BRAF analyses were available from 3063 patients (50%)." (PMID 26121270, 2015). "The concordance between primary tumor and CTCs was high (88.46%- 96.15%) and concerning KRAS and BRAF mutations comparable to previous studies." (PMID 25902072, 2015). "Sorafenib, a multikinase inhibitor targeting BRAF, VEGFR, PDGFR, and c-kit, was associated with unprecedented acceleration of tumor growth in some subjects." (PMID 26525348, 2015). "Genome-scale DNA methylation profiling of 125 CRC cases revealed that CIMP-high tumours have high BRAF mutations (61%), whereas CIMP-low tumours rarely have mutant BRAF, but is associated with high KRAS mutations (45%)." (PMID 25622259, 2015). "CIMP-positive tumours are strongly associated with the MSI phenotype and the presence of BRAF mutations." (PMID 25884297, 2015). "The validity of the data is supported by the detection of BRAF V600E in the tumor tissue of the same patient after the tumor recurred." (PMID 25885250, 2015). "As established in previous studies, majority of tumor cell lines possess a mutation in either KRAS, NRAS or BRAF genes was sensitive to AZD6244 in vitro (IC50 < 1 μM)." (PMID 26567773, 2015). "We also report proof-of-principle data demonstrating the feasibility of a novel microcapillary-based approach for isolating individual CTCs from patient samples, whereby the CTC BRAF status matched that of the originating tumor." (PMID 25807549, 2015). "Recently, it has been reported that vemurafenib, a BRAF inhibitor, resulted in near complete tumor regression in a patient with ATC who had an activating BRAF mutation." (PMID 25940539, 2015). "The average tumour size in BRAF(+) patients was only slightly larger than in BRAF(-) group (16.5 mm vs 13 mm, respectively; the median values 13 mm vs 10 mm, p = 0.004)." (PMID 26177218, 2015). "Previously-described pathways of CRC development have been suggested to result in tumor subtypes that can be distinguished by specific combinations of MSI, CIMP, BRAF-mutation, and KRAS-mutation status." (PMID 26337942, 2015). "Patients with wtKRAS/BRAF tumors had, compared to patients with mutKRAS tumors, more frequently the primary tumor in sigmoideum (40% vs 30%) and rectum (35% vs 24%), and less in right colon (16% vs 37%)." (PMID 26121270, 2015). "The model currently includes LRs already calculated for MSI together with BRAF tumour status, and pending further analysis of datasets it is quite feasible to implement other tumour features mentioned in the previous section." (PMID 25831438, 2015). "The primary tumor was positive for the BRAFV600E mutation, thereby qualifying the patient for treatment with the BRAF inhibitor vemurafenib." (PMID 26105199, 2015). "Patients treated with a BRAF inhibitor had a clinically significant prolongation of survival over 13-16 months as a first line therapy and rapid tumour regression; however, the majority of them acquires resistance to therapy and relapses very rapidly." (PMID 25623468, 2015).
tumor (continued). "Sporadic tumours present a more complicated case whereby consideration must be paid to site-dependence and mutual exclusivity of mutations in the KRAS and BRAF genes and the crosstalk between epigenetics and genetics." (PMID 25622259, 2015). "The results indicated that the expression level of BRAF mRNA was greatly increased in CRC comparing to adjacent non-tumor tissues (42/47, 89.4%, p <0.001) and was inversely related to the expression of miR-378-5p." (PMID 25977643, 2015). "We prove the potential tumor suppressor role of miR-378-5p involved in CRC by identifying one new targeting gene BRAF." (PMID 25977643, 2015). "The multiplexed SCODA mutation detection assay was used to analyze extracted DNA from patient tumor tissue and pre-operative plasma samples for the presence of mutations in KRAS, PIK3CA, BRAF and EGFR as defined in our panel." (PMID 25575824, 2015). "Six of the patients with discordant tumors (22% overall) had a BRAF-negative largest tumor and a BRAF-positive second-largest tumor." (PMID 26448939, 2015). "New studies in patients with RAS mutated tumours employ MEK inhibitors with either ERBB inhibitors or IGF1R inhibitors, and in patients with BRAF mutated tumours employ BRAF/MEK inhibitors." (PMID 25624878, 2015). "This is in line with recently published literature on treatment sequencing, which supports the sequencing of immunotherapy prior to BRAF inhibitors for less aggressive tumours." (PMID 26700304, 2015). "Mutations in these genes were almost exclusively identified in BRAF/KRAS/NRAS mutant tumours, suggestive of cooperative biological effects." (PMID 26506417, 2015). "To this end, we adjusted clinical variables (tumor location and adjuvant chemotherapy) as well as key molecular variables associated with evolution of CRC (MSI, CIMP, KRAS mutation, and BRAF mutation)." (PMID 25875774, 2015). "As such, the present study emphasizes the need to further investigate the direct impact of BRAF and other mutations in the MAPK-pathway on tumor cell glycosylation and immune evasion in CRC patients." (PMID 26172302, 2015). "All UICC stages were included in the sample set; with regard to molecular tumor characteristics, KRAS mutations were present in 27/76 (36%) while BRAF mutations were present in 9/76 (12%) of samples." (PMID 26106602, 2015). "Accordingly, this study verifies the concept that inhibition of TRAP1 chaperoning activity represents a strategy for targeting dependency of BRAF-addicted tumor cells on TRAP1 quality control and antiapoptotic pathway." (PMID 26084290, 2015). "There was one tumor demonstrating mutations in both KRAS and BRAF; this case was excluded from the analysis." (PMID 25929517, 2015). "Of the 96 supplied tumour samples, 83 were BRAF mutant (all V600E) as previously determined by Sanger sequencing." (PMID 26097884, 2015). "Combined BRAF and EGFR inhibition caused a strong synergistic effect in vitro and in xenograft models and resulted in complete inhibition of tumor growth [26••]." (PMID 26617477, 2015). "Patient characteristics in the high vs. low pPI3K signaling CRC cohorts were well balanced in terms of their tumor stage, chemotherapy treatments, and mutational status of the oncogenes KRAS and BRAF." (PMID 25090459, 2014). "Either PD-1 or PD-L1 blockade addition to BRAF inhibition resulted in enhanced response, which slowed tumor growth and enhanced survival." (PMID 25610709, 2014). "11% of the tumors were SOX2 positive, and the expression correlated to tumor grade, TNM stage and BRAF mutation." (PMID 25010701, 2014). "The selective inhibitors of BRAF V600, vemurafenib and dabrafenib have shown major tumour responses in about 50% of patients, resulting in improved progression free (PFS) and overall survival (OS) in MM compared with chemotherapy." (PMID 25437182, 2014).
tumor (continued). "Significant differences were found according to age with a higher proportion of younger patients in the tumor BRAF mutant compared to the BRAF wild-type group (31.5% vs. 15.1% younger than 50 years, respectively)." (PMID 24586605, 2014). "MDM2, MEK and BRAF inhibitor monotherapy conferred tumor volume reductions of 24, 51 and 23%, respectively." (PMID 24810962, 2014). "The treatment-induced tumor regression occurs in the majority of patients; however, acquired resistance to BRAF inhibitors is observed in most of the patients after 6 to 7 months." (PMID 25501056, 2014). "Beyond suppressing tumor growth and inducing apoptosis, the inhibition of oncogenic BRAF evoked an immune-stimulatory effect in mice implanted with TBP-3743." (PMID 24994118, 2014). "Other variables significantly associated with the unsupervised partitions were tumor location, CIMP status and mutated BRAF." (PMID 25083765, 2014). "Recently, certain studies have confirmed that single target inhibitors in a double BRAF-V600E and oncogenic RAS mutation accelerate tumor progression." (PMID 25013473, 2014). "The primary tumor from a second patient was BRAF wild type in the predominant lepidic pattern, but mutant (K601N) only in the minority acinar pattern." (PMID 24742923, 2014). "This concept is based on the fact that BRAF inhibitors (BRAFi) have been shown to significantly affect anti-tumor immunity, essentially creating a more favorable tumor microenvironment early during the course of therapy." (PMID 29250602, 2014). "The recent use of BRAF inhibitor in this patient was assumed to have facilitated a more favorable tumor microenvironment with enhanced antigen presentation to tumor cells that was augmented with the use of SRS." (PMID 25610709, 2014). "Ectopic expression of PDK1 was able to overcome BRAF-induced senescence of melanocytes and promote robust tumor growth in vivo." (PMID 24743024, 2014). "In cancer models: The relative significance of BRAF and RAS mutations in human tumours have been validated in many relevant cancer models." (PMID 25361007, 2014). "Even if the pause from BRAF inhibition allowed sensitive tumours to re-grow, these cells remained responsive to vemurafenib re-administration." (PMID 25344914, 2014). "Liver tumor 1 and the omentum tumor responded to treatment with the BRAF inhibitor vemurafinib, while the others continued growing/progressing during treatment." (PMID 25393105, 2014). "The effect of primary tumor location on OS in patients with BRAF V600E mutant tumors seemed consistent with the observation in the KRAS codon 12/13 wild-type cohort." (PMID 24816724, 2014). "Colombino et al4 have reported BRAF mutant metastases presumably seeded by a BRAF wild-type primary tumour and, more intriguingly, BRAF wild-type metastases in the presence of a BRAF mutant primary." (PMID 24399611, 2014). "In melanoma, the EMT-like switch in phenotype can be driven by environmental pressures such as changes in the cytokine milieu at the tumor site, e.g., due to inflammation, and drug treatments such as inhibition of oncogenic BRAF." (PMID 25566505, 2014). "To reconfirm these results and rule out the fact that we were missing any BRAF mutations due to tumor heterogeneity issues, cancer tissue was re-punched from 2-3 different tumor areas and BRAF analysis was repeated on 400 of these 757 samples." (PMID 25005754, 2014). "Treatment with BRAF inhibitors vemurafenib and dabrafenib resulted in markedly increased numbers of TILs in tumor biopsies obtained pre- and post-treatment in 15 patients." (PMID 24743024, 2014). "MEL9 is characterized by both NRAS and BRAF mutations in founding clone, along with a CTNNB1 P16S mutation that arose later in the evolution of the tumor." (PMID 25393105, 2014). "This case indicates that this specific double mutation of BRAF V600E and KRAS G12A results in a poor clinical course, potentially through the acceleration of tumor progression." (PMID 25013473, 2014).
tumor (continued). "As we had paired tumor samples for 30 patients, we were able to examine intrapatient heterogeneity of mutant BRAF as determined with both pyrosequencing and IHC, and in some cases NRAS mutation as determined with pyrosequencing." (PMID 25526463, 2014). "In summary, KRAS and BRAF have key roles as driver oncogenes in tumourigenesis in many different types of tumours and depending on the tumour type they can differentially regulate key pathways and genes to provide differential biological effects." (PMID 25361007, 2014). "Alternatively, support for LCH as a neoplasm is based on publications that have shown clonality of the CD1a+ cells in LCH using the human androgen receptor assay and BRAF mutation studies." (PMID 25343480, 2014). "A xenograft tumor derived from a second patient resistant to the combination of BRAF and MEK inhibitors contained identical changes." (PMID 24743024, 2014). "BRAF has been associated with dMMR CRCs, with approximately 40% of MSI-high tumours having a BRAF mutation compared to nearly 5% of MSS tumours." (PMID 25361007, 2014). "This review specifically addresses the effects of BRAF-targeted therapy on melanocyte antigen expression and on the tumor microenvironment, and discusses implications of this data." (PMID 29250602, 2014). "All the studied tumours were microsatellite stable and only one, a DERL3-methylated case, had a BRAF mutation." (PMID 24699711, 2014). "In conclusion, the BRAF V600E mutations in PTC and the lymph nodes are independent factors in the prediction of tumor prognosis." (PMID 24396464, 2014). "Autopsy material of this patient showed distinctive BRAF mutant subclones with evidently stronger BRAFV600E expression compared to the rest of the tumor tissue." (PMID 25526463, 2014). "Increased IGF-1R and pAKT levels in a post-relapse human tumor sample were consistent with the proposed role for IGF-1R/PI3K-dependent resistance to BRAF inhibitors." (PMID 24743024, 2014). "Immune/inflammatory pathways were expressed at a lower level in BRAF-mutant tumors due to either suppression of immune/inflammation genes in BRAF-mutant tumors or increased expression by the tumor or by infiltrating lymphocytes in BRAF wild-type tumors." (PMID 25328756, 2014). "Lower rates of BRAF-V600 mutations had also been previously reported after analysis of primary tumors compared to metastasis but was explained by the acquisition and accumulation of BRAF mutant tumor cells during the course of disease." (PMID 24475086, 2014). "Modeling data showed that cells with wild-type BRAF were resistant to AZD6244, when compared to the parent tumor cells with mutant BRAF." (PMID 24884660, 2014). "The overall frequency of KRAS and BRAF mutations in our tumor population was approximately 56% (44% KRAS, 12% BRAF), which is in agreement with previous studies." (PMID 24498230, 2014). "Whereas treatment with BRAF inhibitors at first results in tumor regression in most patients, it is a well-known fact that acquired drug resistance frequently develops." (PMID 24735930, 2014). "Tumours segregated according to their MMR/BRAF phenotype in a consistent trend throughout the period of follow-up, with the MMRp/BRAFV600E trending towards worse prognosis compared to the other three phenotypes." (PMID 25153715, 2014). "The mechanisms of tumor resistance to selective BRAF inhibitors are diverse and complex; however, they frequently share a common endpoint—MAPK pathway reactivation." (PMID 26328215, 2014). "Targeting ERBB2 with lapatinib in combination with the BRAF inhibitor PLX4720 reduced tumor burden and extended latency of tumor regrowth in vivo versus PLX4720 alone." (PMID 24743024, 2014).
tumor (continued). "In patients with BRAF mutant mCRC, the effect of primary tumor location seemed again consistent with the effects observed in patients with KRAS codon 12/13 wild-type tumors." (PMID 24816724, 2014). "The clinicopathological variables included age, gender, TNM staging and tumor location, and the molecular factors included the MMR status, CIMP phenotype and the BRAF mutational status." (PMID 25127039, 2014). "One approach to delay the development of drug resistance and enhance tumor response is to combine a selective BRAF inhibitor with other targeted agents." (PMID 26328215, 2014). "We collected formalin-fixed, paraffin-embedded and fresh frozen tumor samples from AGC patients and analyzed the KRAS, NRAS, BRAF and PIK3CA mutations by direct-sequencing." (PMID 24774510, 2014). "In order to reverse immunosuppression in tumor-bearing hosts, we have evaluated signal inhibition at upstream molecules, such as BRAF-MAPK, STAT3, and Wnt/β-catenin." (PMID 23755373, 2013). "Here we quantified the benefit of adding the everolimus to irinotecan in KRAS and BRAF mutant CRC tumor models." (PMID 23520486, 2013). "Tumor samples were screened for KRAS codon 12, 13 and BRAF V600E mutations by SNaPshot and/or direct sequencing." (PMID 23497191, 2013). "The Tg-Braf mouse model closely recapitulates advanced human BRAF mutant PTCs, in that the tumor cells exhibit characteristic tall cell features, and progress to PDTC." (PMID 23372702, 2013). "The BRAF gene is a marker of adverse prognostic factors, including disease aggressiveness, tumor recurrence, lymph node or distant metastatic disease, and extrathyroidal extension." (PMID 23476646, 2013). "These loci are respectively known to harbour tumour-associated genes, including TIF, BRAF, MLL3, SMO, and MET." (PMID 24289252, 2013). "The interpretation of BRAF mutation as additional risk factor has to be made in the context of MSI status and tumor location." (PMID 24073892, 2013). "Tumor versus paired normal methylation ratios were compared between BRAFp.V600E and BRAF wild types to identify BRAFp.V600E specific DNA methylation." (PMID 24244575, 2013). "In samples where the number of tumor cells is low, IHC-based BRAF testing was suggested to be more sensitive than direct DNA sequencing or high-resolution melting curve analysis." (PMID 24199171, 2013). "FOXD3 expression was detected in all but one of the normal tissue samples, and in three BRAF wildtype tumor samples." (PMID 23324568, 2013). "Gene expession of the two ligands, which are collocalised on chromosome 4q13.3 and produced by tumour cells in autocrine fashion, was tightly correlated and occurred more often in KRAS and BRAF wild type tumours." (PMID 23374602, 2013). "Inter and intra-tumor genetic heterogeneity for BRAF status was also suggested by microdissection technique followed by molecular analysis supporting the need for testing multiple sites in a single patient or to use blood-based mutation-detection method." (PMID 23976959, 2013). "Several studies have reported that the existence of a BRAF mut ation in a primary CRC tumor marks patients who carry an especially poor prognosis, regardless o ftreatment type administration." (PMID 24367680, 2013). "We identified 758 regions with a BRAF mutation-specific methylation change, of which 96.3% had a higher tumor/normal methylation ratio in the BRAF mutant group." (PMID 23324568, 2013). "RET rearrangements (RET/PTC) and BRAF point mutations are genetic alterations occurring in PTC, proposed as tumor markers to refine inconclusive FNC results." (PMID 24267957, 2013). "We evaluated the assay in 6 different tumor types procured from commercial sources for the assay validation and compared our KBN-SNPE (KRAS, BRAF, NRAS Single Nucleotide Primer Extension) mutation assay results to Sanger sequencing and NGS." (PMID 23991070, 2013).